ENSG00000264545 (novel transcript)
Gene: Long non-coding RNA gene on chromosome 9 (21,802,636 to 22,029,594, forward strand). Ensembl gene ENSG00000264545.
Genetic constraint (gnomAD): Missense variants: 107 observed, 110.06 expected, observed/expected ratio (o/e) 0.97, 90% interval 0.83 to 1.14. Synonymous variants: 40 observed, 40.75 expected, observed/expected ratio (o/e) 0.98, 90% interval 0.76 to 1.28.